PTPN2 (protein tyrosine phosphatase non-receptor type 2)
Diseases named in the same sentence as PTPN2 in open-access papers (continued):
Sharing a sentence is not in itself a finding about the gene and the disease.
infection (18 papers, 2012 to 2025). The state of being infected such as from the introduction of a foreign agent such as serum, vaccine, antigenic substance or organism. "Taken together, these data demonstrate that the loss of PTPN2 in epithelial cells disturbs the gut micro-environment, rendering it more susceptible to infection or modulation by commensal bacteria with pathobiont potential." (PMID 40955058, 2025). "PTPN2 helps to mitigate tissue damage associated with hyperinflammation during infection by preventing excessive immune activation." (PMID 41333726, 2025). "As a consequence, combined loss of PTPN2 in IECs and macrophages resulted in devastating disease and an inability to control the infection efficiently." (PMID 36810248, 2023). "Nevertheless, when transferred into Ptpn2ΔIEC mice, Ptpn2-deficient macrophages not only were unable to promote recovery but also further worsened the infection, resulting in a severe delay in recovery and a failure to clear bacterial load." (PMID 36810248, 2023). "To assess why Ptpn2-LysM-Cre mice were more susceptible to C. rodentium infection but, at the same time, able to clear the infection more efficiently, we analyzed the immune cell compartment in these mice over time." (PMID 36810248, 2023). "This was reflected in an at least 3-fold higher geometric mean fluorescent intensity of CD25 in PTPN2-deficient OT-I CD8 T cells at 4 days post infection." (PMID 32726622, 2020). "This was demonstrated in an ex vivo cytotoxicity assay in which PTPN2-deficient versus WT effector T cells at day 7 post Lm-N4 infection were isolated and incubated with peptide-pulsed splenocytes as target cells in specific ratios." (PMID 32726622, 2020). "In contrast, Ptpn2-LysM-Cre mice had severe, early-onset disease characterized by drastic weight loss, elevated disease activity scores, elevated spleen weight at days 7 and 14, and increased bacterial load in stool, liver, spleen, and in mesenteric lymph nodes early in infection." (PMID 36810248, 2023). "Together, these data demonstrate that intestinal epithelial PTPN2 is critical for AMP-mediated defenses in response to mAIEC infection." (PMID 40955058, 2025). "Our findings highlight that intestinal epithelial PTPN2 is crucial for mucosal immunity as it promotes antimicrobial peptide defenses and enhances barrier function during infection from pathobionts such as AIEC, and noninvasive commensals." (PMID 40955058, 2025). "PTPN2-KI and KO cell lines showed increased infection with live SARS-CoV-2 virus compared with IECs carrying WT PTPN2." (PMID 39756517, 2025). "Ptpn2-deficient macrophages are responsible for the faster clearance of the infection in Ptpn2-LysM-Cre mice." (PMID 36810248, 2023). "In line with more severe inflammation during primary infection and a general elevated number of inflammatory cells, Ptpn2-LysMCre mice also suffered from increased lung leukocyte infiltration upon secondary infection with N. brasiliensis." (PMID 34420044, 2022). "The infection efficiency of the PTPN2-gene silencing lentiviral (LW265, LW266, and LW267) and negative control (NC-LW198) vectors in MLE-12 cells was >80%." (PMID 32054021, 2020). "To address this, we used a well-controlled, previously established experimental system for the T cell-specific conditional deletion of PTPN2 in combination with different infection models." (PMID 32726622, 2020). "With IFNγ blockade, genes in cluster 2, including IL18R1, IDO1, CXCL11, CD274 (PD-L1), and PTPN2, were similarly expressed at day 3 post-infection but were more highly expressed at day 7 compared to controls and had increased expression over the day 3 timepoint." (PMID 38950078, 2024). "In contrast, deletion of PTPN2 specifically in epithelial cells rendered the epithelium unable to upregulate antimicrobial peptides and consequently resulted in a failure to eliminate the infection." (PMID 36810248, 2023).
infection (continued). "We observed that the absence of PTPN2 caused a clear shift in the ratio of CD127−KLRG1+ terminal effector versus CD127+KLRG1− memory precursor CD8 T cells upon infection with Lm-N4." (PMID 32726622, 2020). "Having established that PTPN2 deletion did not alter thymocyte and T cell development, we next determined how PTPN2 deficiency impacts T cell differentiation in pathogenic infection." (PMID 32726622, 2020). "Moreover, infected db/db mice exhibited the lowest PTPN2 expression compared to their shame-infection controls and C57 mice." (PMID 27995146, 2016). "Mice lacking intestinal epithelial Ptpn2 suffer from enhanced C. rodentium infection and show delayed clearance of the infection." (PMID 36810248, 2023). "In line with a reduced ability to produce alternatively activated macrophages, infection-induced levels of RELMα were reduced in the BAL of Ptpn2-LysMCre mice, while IL-4 and IL-13 were not affected and IL-6 and IL-17 were elevated." (PMID 34420044, 2022). "tularensis LVS-infection; a significant upregulation of genes involved in RAS pathway including Ccl2, Nfkb, p38 Mapk, Ras, Stat1, Stat3 and Tnf-α; and an upregulated expression of IFN-γ pathway genes such as Bak, Bax, Ifit, Ifn-γ, Irf, Isg, Oas1, Psmb8, Ptpn2, Stat and Tap1." (PMID 37266014, 2023).
inflammation (5 papers, 2010 to 2021). Aberrant reaction of the microcirculation characterized by movement of fluid and leukocytes from the blood into extravascular tissues. "Here, we demonstrated that PTPN2 in DCs affects immune cell infiltrations in the lamina propria, but its presence in DCs seems to be dispensable in the context of colonic inflammation." (PMID 34201918, 2021).
metabolic disorders (4 papers, 2019 to 2023). "Moreover, PTPN2 plays a part in inflammation-associated metabolic disorders, such as diabetes-related diseases." (PMID 36077422, 2022). "In summary, PTPN2, as a critical regulator for metabolic disorder and inflammation, participated in DN." (PMID 30955247, 2019). "Our results demonstrated that PTPN2 gene therapy could exert protective effects on DN via ameliorating metabolic disorders and inhibiting renal STAT‐dependent micro‐inflammation, suggesting its potential role for treatment of human DN." (PMID 30955247, 2019). "We aimed to explore whether PTPN2 gene therapy could improve DN by regulating systemic metabolic disorders and inhibiting local inflammation in kidney." (PMID 30955247, 2019). "Recent studies suggested that protein tyrosine phosphatase non‐receptor type 2 (PTPN2) could ameliorate metabolic disorders and suppress inflammatory responses." (PMID 30955247, 2019). "Thus, our study demonstrates that PTPN2 could ameliorate renal injury and fibrosis via regulation of metabolism disorders and micro‐inflammation." (PMID 30955247, 2019). "Recent studies have shown that PTPN2 exerts protective effects by ameliorating metabolic disorders and suppressing micro-inflammation via the STAT signaling pathway, which suggests PTPN2 is a potential target for the treatment of human DN." (PMID 36077422, 2022).
bacterial infection (3 papers, 2022 to 2025). "This clearly indicates that Ptpn2-deficient and PTPN2-variant cells are defective in autophagy induction on bacterial infection." (PMID 33563644, 2022). "Overall, these data demonstrate that the loss of epithelial PTPN2 increases FD4 permeability after bacterial infection, increasing the tight junction-regulated paracellular barrier permeability but not nonspecific permeability arising from damage to the epithelium." (PMID 40955058, 2025). "However, it is unclear how loss of PTPN2 affects the ability of macrophages to prevent bacterial infections." (PMID 33563644, 2022). "Likewise, autophagy induction following bacterial infection was reduced in macrophages from Ptpn2-Het and completely absent in those from Ptpn2-KO mice." (PMID 33563644, 2022).
hematological diseases (3 papers, 2023 to 2025). "It was then found that PTPN2 was highly expressed in hematologic diseases and bone marrow tissues, and its differential expression in AML patients and normal humans was verified by clinical samples." (PMID 37884566, 2023).
PTPN2 also shares sentences with these, for which no sentence is quoted: ulcerative colitis (8 papers); systemic lupus erythematosus (3); fibrosis (2); Hodgkins lymphoma (2); metabolic syndrome (2); multiple sclerosis (2); myeloma (2); stomach adenocarcinoma (2); T-cell leukemia (2); acute myeloid leukemia (1); acute pancreatitis (1); adenocarcinoma (1); adenovirus infection (1); albuminuria (1); Allergy (1); ankylosing spondylitis (1); astrocytoma (1); atopic dermatitis (1); Atrophy (1); autoimmune enteropathy (1); basal cell carcinoma (1); Behçet’s disease (1); brain glioma (1); Burkitt lymphoma (1); cervical cancer (1); Chlamydia infection (1); Chronic colitis (1); chronic myeloid leukemia (1); colonic disease (1); Colorectal (1).
A further 48 diseases each share a sentence with PTPN2 in 1 paper.